CEACAM8 (CEA cell adhesion molecule 8)
Diseases named in the same sentence as CEACAM8 in open-access papers:
CEACAM8 is named in the same sentence as 148 diseases in open-access papers, as found by Europe PMC text mining. Sharing a sentence is not in itself a finding about the gene and the disease. The quoted sentences say what the papers report.
COVID-19 (38 papers, 2020 to 2025). A disease caused by infection with severe acute respiratory syndrome coronavirus 2. "This study identifies prognostic roles of CEA in COVID-19 patients and implies the potential mechanism of CEACAM8-CEACAM6 in the progression of COVID-19 by regulating the cellular communication of developing neutrophils and type II pneumocyte." (PMID 34217339, 2021). "In COVID-19, the developing neutrophils were found to have cross talk with type II pneumocyte via CEACAM8-CEACAM6." (PMID 34217339, 2021). "In particular, the number of type II pneumocyte was found to significantly increase in COVID-19 and have cross talk with neutrophils via CEACAM8-CEACAM6." (PMID 34217339, 2021). "This study identifies the prognostic roles of CEA in COVID-19 patients and implies the potential roles of CEACAM8-CEACAM6 in the progression of COVID-19 by regulating the cell–cell communication of developing neutrophils and type II pneumocyte." (PMID 34217339, 2021). "In COVID-19, we also found that CEACAM8 is highly expressed in the developing neutrophils/neutrophil progenitors, while CEACAM5 and CEACAM6 are highly expressed in type II pneumocyte." (PMID 34217339, 2021). "When the blood transcriptomic profiles of patients with mild COVID-19 were compared with the profiles from patients with moderate or severe COVID-19, CEACAM8, MMP8, ELANE, LTF, CEACAM6 and MPO were consistently amongst the top SDE genes, with levels increasing with severity and high LFCs." (PMID 35844004, 2022). "We found that PDE5A, ITGB3, CEACAM8, and BPI were hub-shared genes in IS and COVID-19, which were remarkably enriched in pathways such as ECM-receptor interaction and focal adhesion pathways." (PMID 37090981, 2023). "A significant increase in the number of developing neutrophils was found in COVID-19 while CEACAM1, CEACAM6 and CEACAM8 were also significantly co-localized developing neutrophils." (PMID 34217339, 2021). "An analysis of neutrophil adhesion receptors revealed upregulation of CD11b (α-subunit of αMβ2) and CD66b (CEACAM8) but not of CD162 (PSGL-1) in the patients with COVID-19." (PMID 36575689, 2023). "We found that the developing neutrophils/neutrophil progenitors can have the cross talk with type II pneumocyte via CEACAM8-CEACAM6 in COVID-19 but not ALI and IPF." (PMID 34217339, 2021). "CEACAM6 has been identified as having high expression in Type II pneumocytes in COVID-19 patients, the cells targeted by SARS-CoV-250, and it has been suggested that cross-talk between Type II pneumocytes and developing neutrophils in COVID-19 occurs via CEACAM8-CEACAM649." (PMID 35844004, 2022). "The cross talk via CEACAM8-CEACAM6 was found between developing neutrophils and type II pneumocyte in COVID-19 but not ALI and IPF suggesting that during COVID-19 infection process, the differentiated developing neutrophils might regulate some biological processes of type II pneumocyte." (PMID 34217339, 2021).
Sepsis (26 papers, 2008 to 2025). Sepsis is defined as life-threatening organ dysfunction caused by a dysregulated host response to infection. "This study suggests a critical role of LTF, LCN2, ELANE, MPO and CEACAM8 in sepsis and may provide potential diagnostic biomarkers and therapeutic targets for the treatment of sepsis." (PMID 38912048, 2024). "Notably, we identified five key genes (LTF, LCN2, ELANE, MPO, CEACAM8) associated with sepsis using the intersections of the top genes identified by cytoHubba and greenyellow module genes of the WGCNA." (PMID 38912048, 2024). "During sepsis, the bone marrow releases a large amount of immature granulocyte (IGs) through emergency granulopoiesis, such as CEACAM8+Neu, S100A8/9hiNeu, IL1R2+Neu, PADI4+Neu, MPO+Neu and cycling MK167+CYP1B1+Neu." (PMID 40356926, 2025). "Our findings are in line with this phenomenon, showing that CEACAM8 expression is significantly upregulated in patients with sepsis." (PMID 38912048, 2024). "After comparing the results of miRNAs and mRNAs, we identified hsa-miR-342-3p/VNN1, hsa-miR-7108-5p/CEACAM8, hsa-miR-4433b-3p/CEACAM8, and hsa-miR-342-3p/CEACAM8 as interactive pairs related ygiM that were statistically significant in sepsis." (PMID 36212144, 2022). "Subsequently, based on an external validation cohort from our hospital, qRT-PCR demonstrated significant up-regulation on LTF, LCN2, ELANE, MPO, and CEACAM8 in peripheral blood of sepsis patients versus controls, thus further enhancing the reliability of the findings." (PMID 38912048, 2024). "In addition, the expression levels of LTF, LCN, ELANE, MPO, and CEACAM8 were all up-regulated in the peripheral blood of sepsis patients than critical controls in the GSE131761 dataset, which is consistent with the previous findings." (PMID 38912048, 2024). "In summary, our investigation conducted comprehensive bioinformatics analysis on two gene datasets (GSE28750 and GSE74224) and discerned LTF, LCN2, ELANE, MPO and CEACAM8 as key up-regulated genes in sepsis patients when compared with non-sepsis critically ill controls." (PMID 38912048, 2024). "Neutrophils are not only typical pro-inflammatory cells, but also have immunomodulatory properties, so CEACAM8 may be involved in innate immunity in sepsis." (PMID 36212144, 2022). "Among the mRNAs related ygiM we verified, VNN1, CEACAM8, and PGLYRP1 were highlighted about sepsis firstly." (PMID 36212144, 2022). "Thus, the DE genes identified in this study, such as OLFM4, MME, CXCR2,CEACAM8, and ELANE, probably take part in pediatric sepsis development by regulationof neutrophil function." (PMID 33503200, 2021).
colorectal cancer (16 papers, 2012 to 2026). A primary or metastatic malignant neoplasm that affects the colon or rectum. "For example, CEACAM8 is used as a risk signature for inflammation and T immune cell infiltration in colorectal cancer to predict distant metastasis and chemotherapy efficiency." (PMID 36035171, 2022). "CEACAM8 is overexpressed in cancer tissue, in particular lung and colorectal cancer (proteinatlas.org)." (PMID 36409488, 2023). "So, in the present study, CEACAM8, as the great specificity and activated phenotype of neutrophils, was used to detect tumor-infiltrating neutrophils within colorectal cancers (CRC)." (PMID 31456937, 2019). "Not only CEACAM8+ cells, but also CD3+, CD8+, and FOXP3+ cells were observed in colorectal cancer tissues." (PMID 31456937, 2019).
lung cancer (12 papers, 2013 to 2025). A malignant neoplasm involving the lung. "Paraffin sections of lung tissues from 19 donors who underwent surgery for lung resection to treat lung cancer were stained with an IgG control antibody and antibodies specific for CEACAM1, 5 and 6, as well as with an antibody specific for CEACAM8, which is solely expressed in human granulocytes." (PMID 23941132, 2013).
breast carcinoma (10 papers, 2020 to 2025). "Rare PTVs in CEACAM6 and CEACAM8 appear to only be associated with European American breast cancer risk." (PMID 34447411, 2021). "Overall, gene-based aggregation analyses revealed that rare PTVs in CEACAM6, CEACAM7, and CEACAM8 are associated with European American breast cancer risk, and rare PTVs in CEACAM7 are associated with breast cancer risk in African Americans." (PMID 34447411, 2021). "Gene-based analyses determined that rare PTVs in CEACAM6, CEACAM7, and CEACAM8 are associated with European American breast cancer risk, and rare PTVs in CEACAM7 are associated with breast cancer risk in African Americans." (PMID 34447411, 2021). "While a number of PTVs were detected in these genes, two splicing mutations, CEACAM6 c.∗40 + 2T > G and CEACAM8 c.∗40 + 2T > G, were individually determined to be associated with European American breast cancer, both of which affect non-coding exons in the 3′ UTR." (PMID 34447411, 2021). "Here, we report that DOX therapy induced increased circulating levels of the neutrophil markers PGLYRP1, CAMP, MMP9, and CEACAM8 early after a single dose of chemotherapy in breast cancer patients." (PMID 39273682, 2024). "In this study, we evaluated the potential of the neutrophil biomarkers PGLYRP1/TAG7, CAMP/LL37, MMP9, and CEACAM8/CD66b to predict DOX-induced cardiotoxicity in patients with early-stage breast cancer." (PMID 39273682, 2024). "This study aimed to validate mRNA expression of the previously identified biomarkers of DOX-induced cardiotoxicity, PGLYRP1, CAMP, MMP9, and CEACAM8, and to assay their protein expression in the peripheral blood of breast cancer patients." (PMID 39273682, 2024). "The aim of this study was to validate previously determined mRNA biomarkers of DOX-induced presymptomatic cardiotoxicity, PGLYRP1, CAMP, MMP9, and CEACAM8 and to assay their protein expression in breast cancer patients’ circulation." (PMID 39273682, 2024). "Gene-based aggregation analyses revealed that rare PTVs in CEACAM6, CEACAM7, and CEACAM8 are associated with European American breast cancer risk, and rare PTVs in CEACAM7 are associated with breast cancer risk in African Americans." (PMID 34447411, 2021). "Conversely, CEACAM6 and CEACAM8 co-expression inhibits proliferation and invasiveness of breast cancer cells." (PMID 34447411, 2021). "Two stop gain mutations in CEACAM4 were associated with African American breast cancer, and two splicing mutations were associated with European American breast cancer, one in CEACAM6 and another within CEACAM8." (PMID 34447411, 2021). "Higher circulating levels of PGLYRP1, CAMP, MMP9 and CEACAM8 prior to and after the first dose of DOX chemotherapy may further contribute to progressive cardiovascular disorders in breast cancer survivors and may potentially predict the risk of both acute subclinical and late cardiotoxicity." (PMID 39273682, 2024). "In this study we analyzed peripheral blood samples from 40 patients with early-stage breast cancer treated with DOX-based chemotherapy for protein and mRNA expression of PGLYRP1, CAMP, MMP9 and CEACAM8." (PMID 39273682, 2024). "According to such additional filter, six cancer-specific proteins in colon cancer (CEACAM8, CDH17, GLOD5, PPM1E, TRIM16, EPCAM) and one in breast cancer (CCR9) were identified." (PMID 36243758, 2022). "Residues in CEACAM6 and CEACAM8 have been identified that are critical for CEACAM6 homodimerization as well as the formation of CEACAM6 and CEACAM8 heterodimers, which is important in preventing breast cancer cell proliferation." (PMID 34447411, 2021). "According to such parameters, six cancer-specific proteins in colon cancer (CEACAM8, CDH17, GLOD5, PPM1E, TRIM16, EPCAM), one in breast cancer (CCR9) and none in prostate cancer were identified." (PMID 36243758, 2022).
Obesity (4 papers, 2021 to 2024). Accumulation of substantial excess body fat. "Many of the upregulated immature neutrophil genes (e.g., OLFM4, DEFA1, ELANE, CEACAM6, CEACAM8, CTSG) have been found to be differentially expressed in persons with obesity and type 2 diabetes, both common comorbidities with psychotic disorders." (PMID 37147304, 2023).
autoimmune disease (3 papers, 2018 to 2024). A disorder resulting from loss of function or tissue destruction of an organ or multiple organs, arising from humoral or cellular immune responses of the individual to their own tissue constituents. "The secretion of soluble CEACAM8 could trigger an excessive immune response, especially in autoimmune diseases such as rheumatoid arthritis." (PMID 39609876, 2024). "Finally, we are measuring concentrations of soluble CEACAM8 in samples from patients suffering from other autoimmune diseases." (PMID 31258530, 2019).
gastric adenocarcinoma (3 papers, 2020 to 2024). "In female gastric adenocarcinoma, the abundance of CEACAM8-positive tumor-infiltrating neutrophils had a specific impact on the prognosis." (PMID 39609876, 2024).
influenza (3 papers, 2019 to 2024). An acute viral infection of the respiratory tract, occurring in isolated cases, in epidemics, or in pandemics; it is caused by serologically different strains of viruses (influenzaviruses) designated A, B, and C, has a 3-day incubation period, and usually lasts for 3 to 10 days. "We found that the M59 hub gene CEACAM6 and its co-expressing CEACAM8 were both up-regulated in the influenza dataset." (PMID 38071387, 2023).
ovarian carcinoma (3 papers, 2022 to 2023). A malignant neoplasm originating from the surface ovarian epithelium. "CD11b (ITGAM) and CD66b (CEACAM8), as surface molecular markers of neutrophil degranulation, were highly expressed after ovarian cancer organoids stimulation, which indicated that ovarian cancer cells could activate neutrophils." (PMID 37644468, 2023).
viral infection (3 papers, 2020 to 2021). "Markers of polymorphonuclear myeloid-derived suppressor cells (PMN-MDSCs), CEACAM8 (CD66B) and OLR1 (LOX-1), and markers of monocytic MDSCs (M-MDSCs), IL-4R, ITGAM (CD11B), including a functional marker of MDSCs, ARG1, were positively correlated with the severity of viral infection." (PMID 33765435, 2021).
atherosclerosis (2 papers, 2022 to 2023). A disease characterized by the build-up of fatty material and calcium deposition in the arterial wall resulting in partial or complete occlusion of the arterial lumen. "CEACAM8 is reported to be associated with atherosclerosis and type 2 diabetes." (PMID 37090981, 2023).
heart failure (2 papers, 2022 to 2024). Inability of the heart to pump blood at an adequate rate to meet tissue metabolic requirements. "CEACAM8 was one of the plasma proteins related to inflammation identified as key predictive potential biomarkers predictive of heart failure in 3 independent international cohorts." (PMID 39273682, 2024). "Signs of heart failure and LVEF decrease to <40% was recorded in 4 patients with elevated mRNA and protein expression of PGLYRP1, CAMP, MMP9 and CEACAM8 at baseline and after the initial chemotherapy dose." (PMID 39273682, 2024).
carotid atherosclerosis (1 paper, 2021). A thickening and loss of elasticity of the walls of carotid arteries that occur with formation of atherosclerotic plaques. "Moreover, CEACAM8-positive neutrophils have been demonstrated in carotid endarterectomy samples from patients with carotid atherosclerosis." (PMID 34639156, 2021).
glioblastoma (1 paper, 2025). The most malignant astrocytic tumor (WHO grade IV). "Several studies have hinted to the importance of IL-1 signaling in pNET microenvironment, while sequencing showed the relevance of CD16, IL-1β and NF-κB signaling pathway, while PLAUR alterations were identified in Glioblastoma and CEACAM8 in cervical small cell neuroendocrine carcinomas." (PMID 39851539, 2025).
prostate tumors (1 paper, 2018). "Notably, markers of chronic inflammation, such as CD3 receptors or CD68, are strongly correlated with NKX3.1 status in human prostate tumors, which is not the case for markers of acute inflammation such as CEACAM8 or CD177." (PMID 30266798, 2018).
tumor (194 papers, 2011 to 2026). "So CEACAM8-positive TINs were observed up-regulated in tumor tissues relative to match normal tissues." (PMID 31456937, 2019). "In the discovery set (TCGA), we performed X-tile program to determine the cut-off values of CEACAM8 mRNA levels in tumor tissue, which were 1.92." (PMID 31456937, 2019). "The ability of tumor-infiltrating neutrophils expressing CEACAM8 to regulate the immune-cell infiltration may account for this survival profit." (PMID 31456937, 2019). "TIMELESS expression was significantly negatively correlated with neutrophil biomarkers (CEACAM8) and dendritic cell biomarkers (HLA-DPB1, HLA-DQB1, HLA-DRA, HLA-DPA1, CD1C) in TCGA LUAD tumor tissues." (PMID 38261568, 2024). "In this study, we have investigated the survival impact of CEACAM8-positive neutrophils in CRC and illustrated the correlation of tumor-infiltrating inflammatory and immune cells with prognosis." (PMID 31456937, 2019). "We identified NETs showing positivity for citrullinated histone H3 (Cit-H3) and granulocytes expressing CD66b (CEACAM8) with multiplex immunohistochemistry and used digital image analysis and machine learning tools to calculate their densities in tumor samples." (PMID 41942612, 2026). "Moreover, IHC staining of the tumor tissues derived from shNKX2‐1/LL2 cells orthotopically implanted into mouse lungs also showed elevated expression of ITGAM, CEACAM8, ELANE, and CXCR2 as compared to the control." (PMID 39113226, 2024). "In previous studies, we showed that NEO-201 specifically recognizes a tumor-associated variant of CEACAM5 and CEACAM6, which is not expressed in normal tissues, and proved that NEO-201 binds to both mammalian-expressed recombinant human CEACAM5 and CEACAM6 but not to CEACAM1 or CEACAM8 by ELISA." (PMID 36291783, 2022). "We observed an overexpression of neutrophil intracellular marker protein (MPO) and cell surface marker proteins (CEACAM8, ITGAM and ITGB2) in early stage GBC in comparison to GSD (non-tumor controls) suggesting neutrophil infiltration in tumor tissue." (PMID 36686780, 2022).
cancer (49 papers, 2010 to 2026). A tumor composed of atypical neoplastic, often pleomorphic cells that invade other tissues. "The results showed that the HIV peptides with the highest homology to TAAs identified in breast (CCR9), colon (EPCAM, GLOD5, CEACAM8) as well as prostate (NDUFS2) cancer and linked to most frequent HLA alleles (01:01; 02:01 and 24:02), are highly conserved across HIV isolates." (PMID 36243758, 2022). "Top five miRNA binding sites for both CEACAM6 and CEACAM8 and previous cancer associations." (PMID 34447411, 2021). "Based on miRDB rankings, the top five microRNAs that bind to the 3′ UTRs of CEACAM6 and CEACAM8 have previous links to cancer; thus, disrupted microRNA binding likely leads to aberrant CEACAM6 and CEACAM8 expression." (PMID 34447411, 2021). "Little is known about the role of CEACAM8 in cancer, making it hard to assess the consequences of an insulin-induced CEACAM8 upregulation." (PMID 33690729, 2021).
infection (22 papers, 2013 to 2026). The state of being infected such as from the introduction of a foreign agent such as serum, vaccine, antigenic substance or organism. "In septic conditions, CEACAM8 is overexpressed, prompting neutrophils to localize to the site of infection, release inflammatory mediators and work to clear pathogens." (PMID 38912048, 2024). "Levels of CD11b (CR3A/ITGAM [integrin alpha M]), mediating leukocyte adhesion, and the degranulation marker CD66b (CEACAM8) were also increased compared to the mock-infection results, with significantly elevated CD66b levels seen upon C. albicans infection." (PMID 33024045, 2020).
bacterial infection (4 papers, 2014 to 2023). "Our results suggest a new mechanism by which granulocytes reduce pro-inflammatory immune responses in human airways via secretion of CEACAM8 in neutrophil-driven bacterial infections." (PMID 24743304, 2014).
CEACAM8 also shares sentences with these, for which no sentence is quoted: gastric cancer (20 papers); melanoma (9); glioma (8); asthma (6); colon cancer (6); hepatocellular carcinoma (6); cervical carcinoma (5); lung adenocarcinoma (5); bladder cancer (4); breast tumors (4); lupus (4); prostate carcinoma (4); psoriasis (4); B-cell lymphoma (3); esophageal adenocarcinoma (3); lymph node metastasis (3); non-small cell lung carcinoma (3); renal cell carcinoma (3); rheumatoid arthritis (3); thyroid cancer (3); acute coronary syndrome (2); acute respiratory distress syndrome (2); adenocarcinoma (2); allergic asthma (2); bronchiectasis (2); chronic obstructive pulmonary disease (2); Cirrhosis (2); endometriosis (2); infectious disease (2); ischemic stroke (2).
A further 98 diseases each share a sentence with CEACAM8 in 2 papers or fewer.